RPS6 (ribosomal protein S6)
Diseases named in the same sentence as RPS6 in open-access papers (continued):
Sharing a sentence is not in itself a finding about the gene and the disease.
cancer (continued). "To investigate the mechanism of ribosome synthesis in HCC, we performed RIP-seq with RPS6 in cancer cell lines and determined global transcriptome binding with RPS6." (PMID 33710804, 2021). "Functional implications of RPS6 in cell cycle regulation were also demonstrated by RPS6-KD in a variety of cancer cells." (PMID 35008473, 2021). "In this review article, we reviewed the current information about the transcriptional regulation, upstream regulators, and extra-ribosomal roles of RPS6, with a focus on its involvement in cancer." (PMID 35008473, 2021). "Induction of the epithelial–mesenchymal transition (EMT) markers suggests that overexpression of RPS6 contributes to metastasis of cancers." (PMID 35008473, 2021). "RPS6 is used as a readout of the mechanistic/mammalian target of rapamycin complex 1 (mTORC1) activity in many diseases, including cancers, since alleviated activity of mTORC1, an upstream regulator of RPS6, is commonly found in many types of cancer cells." (PMID 35008473, 2021). "The level of RPS6 or p-RPS6 was also correlated with the pathological grade and/or disease progression in distinct human cancers." (PMID 35008473, 2021). "Here, we performed RNA immunoprecipitation sequencing (RIP) with RPS6 in cancer cell lines, Hep3B, HCT116, DU145, and SW1990, to identify snoRNAs involved in ribosome biogenesis." (PMID 33710804, 2021). "Knockdown experiments have demonstrated that RPS6 itself, not only p-RPS6, is indispensable for the proliferation or survival of various cancer cells." (PMID 35008473, 2021). "It has been reported that RPS6 phosphorylation regulates malignant phenotypes in several cancers induced by Akt-mTOR signaling." (PMID 34831193, 2021). "Our discovery of DRAM1 inhibited rpS6 phosphorylation via the PI3K-Akt-mTORC1-rpS6 pathway provided a mechanistic possibility for understanding the role of DRAM1 in human cancer." (PMID 30902093, 2019). "This rpS6 “phosphorylation” regulates cell size, cell proliferation, glucose homeostasis and cancer defense." (PMID 30969964, 2019). "Next, we investigated the impact of rpS6 expression on the RCC related cancer specific survival and progression free survival by multivariate analysis." (PMID 26506236, 2016). "A trend towards an increase in phosphorylation of AKT, RPS6, and 4EBP1 was seen in the Fc+Pik3caH1047R and Fc+Pik3cap110* cancers." (PMID 26863299, 2016). "Clinical investigations even showed the drug resistance with rpS6 hyperphosphorylation in several kinds of malignant tumors." (PMID 26490682, 2015). "In addition, the mTORC1 inhibitor rapamycin significantly inhibits mTORC1 activity in cancer and RPS6 phosphorylation levels in bladder cancer." (PMID 36617563, 2023). "Furthermore, studies showed that inhibitors of PIM kinases reduce the phosphorylation status of ribosomal protein S6 in multiple cancer types." (PMID 37943821, 2023). "Considering that rpS6 is a downstream effector of both the ERK and the mTOR pathways linked to cancer development and metastasis, the mTOR-selective inhibitor rapamycin was used to investigate the involvement of the mTOR pathway in the EGF-mediated signalling transduction." (PMID 35884900, 2022). "Substantial evidence suggests that RPS6 is a potential therapeutic target, and knockdown experiments have demonstrated that RPS6 itself, not only p-RPS6, is indispensable for the proliferation or survival of various cancer cells." (PMID 36672551, 2022). "Substantial evidence suggests that RPS6 is a potential therapeutic target against cancers." (PMID 35008473, 2021). "This motivates us to investigate the current knowledge of RPS6 functions in cancer." (PMID 35008473, 2021). "The siRNA- or shRNA-based RPS6-KD has demonstrated anticancer effects in various cancer cells." (PMID 35008473, 2021). "Twelve snoRNAs were found to co-exist in 4 cancer cell lines using RPS6 pull-down assays." (PMID 33710804, 2021). "We also discussed the therapeutic potential of RPS6 in cancer." (PMID 35008473, 2021).
cancer (continued). "In addition, substantial evidence from RPS6 knockdown experiments suggests the potential role of RPS6 in maintaining cancer cell proliferation." (PMID 35008473, 2021). "In addition, both the triple combination and RPS6-KD with VA and tamoxifen reduced the cancer stem cell (CSC) population in TNBC cells." (PMID 35008473, 2021). "The positive and negative feedback and/or feedforward mechanisms and novel regulatory pathways controlled by RPS6 may provide alternative therapeutic interventions to overcome the current limitations in cancer treatment." (PMID 35008473, 2021). "The overexpression of RPS6 confers intrinsic or acquired drug resistance to cancer cells." (PMID 35008473, 2021). "Related studies have shown that RPS6 may play an important role in the migration and invasion of malignant tumors." (PMID 32862831, 2020). "However, further study is needed to characterize the molecular mechanisms of RPS6 in cancers fully, and in vivo studies are required to confirm these results followed by consideration of human trials." (PMID 32862831, 2020). "Finally, DRAM1 decreased cell viability upon serum starvation and inhibited rpS6 phosphorylation in human cancer cells." (PMID 30902093, 2019). "The addition of microbubbles, or surpassing clinical diagnostic intensities resulted in increased permeabilization efficiency, reduced cell viability and a change in phosphorylation status of p38, ERK1/2, CREB, Akt, STAT3, ribosomal protein S6 and eIF2α in the cancer cells." (PMID 31284599, 2019). "Taken together, these data suggest that rpS6 phosphorylation may be a biomarker of response for cancer cells that are responsive to the combined inhibition of Src and the MAPK pathway." (PMID 29487290, 2018). "As we observed that phosphorylation of AKT and ribosomal protein S6 were decreased following lipin-1 silencing, we hypothesized that lipin-1 silencing could potentiate the anti-proliferative effect of rapamycin on cancer cells." (PMID 25834103, 2015). "Recently, the potential implication of RPS6 in human cancer was revealed by knockdown experiments." (PMID 25955731, 2015). "Collectively, targeting RPS6 may provide alternative therapeutic regimen to treat human cancers with high level of RPS6." (PMID 25955731, 2015). "This may indicate that RPS6 could be a key anti-cancer factor of Amuc_1100." (PMID 41170411, 2025). "In a high-quality haplotype of sika deer antlers based on chromosome-scale genomes, RPS6 was identified as one of several extended gene families that may help velvet antlers grow rapidly without causing cancer." (PMID 38834950, 2024). "Additionally, RPS6 plays important roles in ribosome biogenesis, protein translation, cell proliferation, cell growth, DNA repair, apoptosis, cell differentiation, and glucose metabolism in both normal and cancer cells." (PMID 36672551, 2022). "RPS6-knockdown (KD) is known to downregulate phospho (p)-RB in various cancer cells; however, it is elusive whether such a positive feedback loop between RPS6 and the p-RB level is involved in cancer progression." (PMID 35008473, 2021). "In addition to its role in protein synthesis, RPS6 may activate various pathways to induce the oxidative stress response, drug resistance, cancer stem cell stemness, and cell-cycle arrest." (PMID 35008473, 2021). "Additionally, RPS6 has been proposed as a predictive biomarker in cancers." (PMID 35008473, 2021). "In addition, the roles of RPS6 in conjunction with NOTCH-related cancers remains to be determined." (PMID 35008473, 2021). "Additionally, DRAM1 inhibited rpS6 phosphorylation in several human cancer cells." (PMID 30902093, 2019). "To identify potential effectors of this phenotype, we examined the mTOR pathway, a well-established driver of translation in cancer, which is known to phosphorylate 4E-BP1 and ribosomal protein S6 to enhance translation efficiency." (PMID 40805278, 2025).
cancer (continued). "Ribosomal protein S6 (p-S6) and p21 (also known as CDKN1A) are two proteins known to play central roles in other cancers." (PMID 38673889, 2024). "From the lncRNA-mRNA pathway network, PYCARD, RIPK2, and CASP1 were found to be significantly enriched in the NOD-like receptor signaling pathway, whereas MAP2K2, LUM, RPS6, PDCD4, TWIST1, and HIF1A were significantly enriched in proteoglycans in cancers." (PMID 36619896, 2022). "Ribosomal protein S6 (RPS6) controls mRNA translation, and phospho-RPS6 has been identified as a surrogate marker of the activated PI3K/AKT/mTORC1 pathway found in many cancer types." (PMID 36619896, 2022). "RPS6-KD downregulated DR4 and desensitized these cancer cells to TRAIL-dependent apoptosis (see Section 5.2.7." (PMID 35008473, 2021). "Activation of P70-S6K1 leads to increased activity of ribosomal protein S6 (RPS6), which induces translation of HIF-1α mRNA into protein, thus serving as the major determinant of the rate of HIF-1α protein synthesis in many cancers." (PMID 31083403, 2019). "The invasive cancers observed in Pc1Pik3caH1047R mice possess activation of the PI3K signaling cascade with downstream phosphorylation of AKT and RPS6." (PMID 26436951, 2015). "Vice versa, up-regulation of RPS6 and down-regulation of PTEN and PIK3R1 in TSCCs is typical of aggressive cancers." (PMID 24427739, 2013). "Furthermore, we also observed that genes in the pathway “Proteoglycans in cancer” (KEGG), namely RPS6 and IHH, were significantly over-represented." (PMID 40232348, 2025). "Examples of RPLs and RPSs include RPL15, RPL19, RPS6 and RPS15A, which have been associated with a negative prognosis in malignant neoplasms of the digestive system." (PMID 38804617, 2024). "RpS6 (ribosomal protein S6) is another protein of interest; it is a downstream effector of both the ERK and the mTOR pathways, and it is essential for the protein synthesis required during cancer progression." (PMID 35884900, 2022). "Taken together, these results suggest that MAP2K2, LUM, RPS6, PDCD4, TWIST1, and HIF1A may play important roles in DMD pathophysiology by regulating the MAPK pathway and proteoglycans in cancer." (PMID 36619896, 2022). "Moreover, in cells expressing the cancer-derived K57N mutant (termed K57N cells), MEK1(K57N), ERK, and rpS6 were persistently phosphorylated and therefore Egr1 was constitutively expressed irrespective of EGF stimulation." (PMID 35831322, 2022). "In our proposed DMD-related lncRNA-mRNA pathway networks, PYCARD, RIPK2, and CASP1 were significantly enriched in the NOD-like receptor signaling pathway, whereas MAP2K2, LUM, RPS6, PDCD4, TWIST1, and HIF1A were significantly enriched in proteoglycans in cancers." (PMID 36619896, 2022). "Additionally, phospho (p)-RPS6 has been recognized as a surrogate marker for the activated PI3K/AKT/mTORC1 pathway, which occurs in many cancer types." (PMID 35008473, 2021). "To investigate whether DRAM1 could inhibit the phosphorylation of rpS6 in human cancer cell lines, we overexpressed DRAM1 in human cancer cells." (PMID 30902093, 2019). "We believe that rpS6 phosphorylation could serve as the starting point to elucidate the functions of DRAM1 and its role in human cancer." (PMID 30902093, 2019). "Finally, human cancer cells Hela, SW480, and HCT116 were transfected with the FLAG-DRAM1 plasmid and phosphorylated rpS6 and rpS6 were detected with Western blot analysis." (PMID 30902093, 2019). "Ribosomal protein S6 is a component of the ribosome phosphorylated by S6 kinase, which is a component of the PI3K-mTOR axis, over-activation of which is another common feature of cancer cells." (PMID 28781988, 2017). "Non-neoplastic ducts can be seen entrapped within the carcinoma and are highlighted by their absence of staining for phospho RPS6 and Ki67." (PMID 26436951, 2015).
cancer (continued). "Thus, our results identify that the class I PI3K-Akt-rpS6 pathway is regulated by DRAM1 and may provide new insight into the potential role of DRAM1 in human cancers." (PMID 30902093, 2019). "However, when used alone, it has often limited effects mainly due to the loss of negative feedback loops in cancer cells leading to reactivation of AKT and ribosomal protein S6." (PMID 25834103, 2015). "Therefore, targeting RPS6 and its downstream rather than upstream effectors might be an alternative approach for cancer treatment." (PMID 35008473, 2021). "Phosphorylation sites on 4EBP1 (gene name EIF4EBP1) or Ribosomal S6 (gene name RPS6), which are known to be downstream of PI3K/mTOR, did not correlate with the responses of our cancer cell panel to the PI3K/mTOR inhibitor PI-103." (PMID 23628362, 2013). "Notably, along with our study, we found that expression of p-RPS6, E2F1, FOXM1, and WEE1 protein was elevated significantly in de-differentiated LPS cancer cells, relative to nonmalignant ASC52telo cells." (PMID 33564073, 2021).
infection (21 papers, 2008 to 2025). The state of being infected such as from the introduction of a foreign agent such as serum, vaccine, antigenic substance or organism. "A previous study revealed that the RPS6 mRNA expression and protein levels in Nicotiana benthamiana increased during infection with the turnip mosaic virus (TuMV), tobacco etch virus (TEV), and tobacco mosaic virus (TMV)." (PMID 39336771, 2024). "We used whole-mount embryo immunofluorescent staining of phosphorylated ribosomal protein S6 (phospho-S6) as a readout for mTOR activity after infection of miR-126 and tsc1a knockdown embryos with M. marinum." (PMID 38307625, 2024). "FMDV infection did not affect the protein expression of p70S6K1 and rpS6, while it enhanced the phosphorylation of p70S6K1 and rpS6 as the infection progressed." (PMID 36735752, 2023). "Of these genes, ribosomal protein genes such as RPS4X and RPS6 also showed downregulation in expression levels, suggesting the importance of ribosomal protein genes during infection." (PMID 35464437, 2022). "Especially, the intensity of the lower of the two phospho-rpS6 bands was increased at 16 and 24 h after infection (lanes 8, 9)." (PMID 35370781, 2022). "With respect to the phosphorylation of rpS6, we found that SKI-II caused a significant reduction at 16 and 24 h after infection (lanes 8, 9 compared to 16, 17) indicating reduction of the translational capacity of the cells." (PMID 35370781, 2022). "We observed that knockdown of RPS6 decreased the percentage of latently infected cells and increased that of productively infected cells, while the overall infection (latent plus productive infections) rate was largely the same." (PMID 33504604, 2021). "Pharmacological inhibitions of the mTORC1/S6K/RPS6 pathway inhibits the infection or pathogenesis of these pathogens." (PMID 35008473, 2021). "We observed that under all the conditions tested (mock infection, 6 hpi, and 18 hpi), cytoplasmic ribosome proteins from the small (RPS6, RPS14, and RPS3) and large (RPL23a, RPL24, and RPL8) subunits were enriched in the ASFV-DP fraction." (PMID 29021398, 2017). "Following WNV infection of control MEF cells, total rpS6 expression was increased at 24 and 48 h post-infection, while phosphorylated rpS6 at S235/236 was increased at 48 h post-infection when compared to mock-infected cells." (PMID 27763553, 2016). "Bacteriophage T7 modifies ribosomal protein S6, S1 and translational initiation factors by phosphorylation upon infection of E. coli." (PMID 18598358, 2008). "DK212 infection dramatically induced phosphorylation of rpS6 compared with DK383." (PMID 36059479, 2022). "Mounting evidence suggests the roles of RPS6 during pathogen infection." (PMID 35008473, 2021). "Initially, the presence of ribosomes and specific ribosomal subunits such as RPS6, RPS16, and RPL3 and viral mRNA within these sites indicated compartmentalization of translation during infection." (PMID 38421168, 2024). "Our data indicated that infection of lung tissue and DEF with either a highly virulent or avirulent H5N1 virus favored ubiquitinylation of Akt, mTOR, p70S6K, and rpS6." (PMID 36059479, 2022). "Accordingly, phosphorylation of S6K1 substrate ribosomal protein S6 (RPS6) at S235, S236, S240, and S244 was augmented during infection." (PMID 32479529, 2020). "However, no obvious changes in phosphorylation level of RPS6 after infection with these viruses were observed." (PMID 30340407, 2018). "Among many ribosomal proteins, 40S ribosomal protein S6 (RPS6, Niben101Scf01293g03017.1), which was found to be the strongly up-regulated protein and down-regulated in phosphorylation under PSV-P or PSV-P and satRNA infection in our analysis, has attracted significant attention." (PMID 30340407, 2018).
adenocarcinoma (2 papers, 2015). A common cancer characterized by the presence of malignant glandular cells. "The adenocarcinoma cells demonstrate increased phosphorylated AKT and RPS6 as expected given the presence of the constitutively active PI3K in these cells." (PMID 26436951, 2015).
brain disease (1 paper, 2021). "Disorders within the mTOR and MAPK pathways are characteristic of patients with ASD (e.g., an increase in protein p-EIF4E, rpS6, ERK1–2 in blood) and are an important target in the search for a treatment for this brain disease." (PMID 34579089, 2021).
cardiac diseases (1 paper, 2025). "While RPS11 has not been previously reported in cardiac diseases, other ribosomal proteins(RPS6) have been associated with cardiac conditions." (PMID 40114920, 2025).
CNS tumors (1 paper, 2015). "The analysis of mTORC1-activity in patient tissue should be performed with caution since a high number of tumors also show strong expression of phospho-RPS6 (Ser235/236), phospho-RPS6 (Ser240/244) and phospho-4EBP1 (Thr37/46) on non-neoplastic cells in CNS tumors." (PMID 25993328, 2015).
RPS6 also shares sentences with these, for which no sentence is quoted: oral squamous cell carcinoma (4 papers); pancreatic neuroendocrine tumor (3); renal carcinoma (3); triple-negative breast carcinoma (3); liver cancer (2); myeloid leukemia (2); neurodevelopmental disorder (2); premature ovarian failure (2); tuberous sclerosis (2); vulvar squamous cell carcinoma (2); anaplastic astrocytoma (1); anaplastic thyroid cancer (1); angiomyolipoma (1); Anxiety (1); autoimmune myocarditis (1); B-cell non-Hodgkin lymphoma (1); bacterial infection (1); brain injury (1); cerebellar ataxia (1); chondrosarcoma (1); chronic kidney disease (1); chronic myeloid leukaemia (1); colon adenocarcinoma (1); diabetic retinopathy (1); Down syndrome (1); Dyskinesia (1); dyslipidemia (1); dysplasia (1); epileptic seizure (1); epithelial dysplasia (1).
A further 39 diseases each share a sentence with RPS6 in 1 paper.